TRIM16 (tripartite motif containing 16)
Diseases named in the same sentence as TRIM16 in open-access papers (continued):
Sharing a sentence is not in itself a finding about the gene and the disease.
cancer (continued). "Two of them (TRIM16 and TRIM50) are considered tumor suppressive, while others (TRIM11, TRIM25, TRIM27, TRIM52 and TRIM59) instead promote oncogenesis in this type of cancer." (PMID 34208621, 2021). "Overexpression of TRIM16 in SKOV3 cells also downregulated protein levels of the matrix metalloproteases MMP2 and MMP9, which degrade the extracellular matrix, indicating a role of TRIM16 in cancer cell invasion." (PMID 34208621, 2021). "In addition, TRIM16 is essential for the NRF2/p62-mediated autophagy/aggrephagy activation, promoting protein homeostasis (proteostasis) and cancer cell survival during oxidative/proteotoxic stress." (PMID 32703253, 2020). "TRIM16, also named as the estrogen responsive B box protein (EBBP), has been shown to play a negative role in the development and progression of several cancers." (PMID 31820796, 2019). "Taken together, our data reveal a novel mechanism, by which cells overexpressing TRIM16 can induce apoptosis in cancer cells, but not in non-malignant cells." (PMID 23404198, 2013). "Although these data suggest that TRIM16 is a prosurvival protein through the regulation of autophagy, NRF2-p62, and ubiquitin system, it has not been characterized if TRIM16 is involved in the regulation of inflammasome activation and pyroptosis while suppressing cancer cell cytotoxicity." (PMID 32703253, 2020). "In contrast, treatment with up to 10 μm 13-cis-RA did not change the TRIM16 cytoplasmic or nuclear levels, or cell proliferation in MET-1 cancer cells." (PMID 22009481, 2012).
tumor (30 papers, 2012 to 2025). "This protein is encoded by TRIM16 gene on chromosome 17p11.2 and some previous research has attributed the tumor suppressive role to it." (PMID 34452557, 2021). "This suggests that loss of a single copy of TRIM16 increases tumour development and reduces latency, but loss of both copies abrogates this result." (PMID 31342168, 2019). "A prior investigation uncovered that a long noncoding RNA specifically associated with gastric cancer distant metastasis correlates with TRIM16 expression, which has been demonstrated to promote tumor cell invasiveness in vitro." (PMID 40936722, 2025). "This molecular pathway reveals a novel mechanism by which lncPTEN1 functions as a suppressor of tumor metastasis through regulation of the TRIM16-Vimentin axis." (PMID 40521243, 2025). "Decreased TRIM16 expression also led to the accumulation of β-catenin and ultimately exerted a tumor suppressive effect." (PMID 40936722, 2025). "TRIM16 was found to be upregulated in HCC tissues, and its high expression was associated with poor prognosis, higher tumor grade and stage for HCC patients." (PMID 38581570, 2024). "Tripartite Motif Containing 16 (TRIM16) is a member of the TRIM protein family which is known to play a suppressor role in development of numerous tumor types." (PMID 34452557, 2021). "TRIM16 encodes a protein of the TRIM family, which is involved in the regulation of cell cycle, proliferation, differentiation, ubiquitination, apoptosis, tumor suppressor functions and oncogenesis." (PMID 34639015, 2021). "The expression level of TRIM16 of fresh primary tumor and adjacent normal tissues in 40 GC patients was evaluated by real-time quantitative PCR method." (PMID 34452557, 2021). "Next to an endogenous tumor-suppressing role in melanocytes, TRIM16 has also an exogenous effect through keratinocytes." (PMID 34639015, 2021). "We have also shown that TRIM16 acts as a tumour suppressor and reduces cell motility via down-regulation of vimentin expression." (PMID 33184347, 2020). "Overexpression of TRIM16 can inhibit cell proliferation in most tumors, and this effect is often called tumor suppression." (PMID 33173411, 2020). "Previously, we have also shown that the putative tumour suppressor, TRIM16, is upregulated during keratinocyte differentiation, and TRIM16 protein expression is lost during the progression of normal skin through SCC development." (PMID 31342168, 2019). "Altogether, we show in tumor model that TRIM16 modulates NRF2‐p62 signaling and ubiquitin system to protect the cells against oxidative stress‐induced toxicity." (PMID 30143514, 2018). "We investigated the pattern of TRIM16 expression by immunohistochemistry (IHC) among 91 patient tumor samples, representing all clinical stages." (PMID 25333256, 2014). "Like TRIM24/TIF1α and TRIM32, TRIM16 has been shown to suppress tumour progression through regulatory pathways involved in growth inhibition, migration, differentiation and apoptosis." (PMID 23404198, 2013). "Similar to these proteins, TRIM16 acts as a tumour suppressor protein through inhibitory effects on cell growth, migration, proliferation, as well as induction of apoptosis." (PMID 23404198, 2013). "Our study establishes a Tumor Microenvironment-derived Prognostic Model (MPM) that integrates eight TME-associated genes (CXCL12, GZMB, ITPR2, LYN, RAB9B, RGMB, RUFY4, TRIM16) to stratify AML patients into distinct risk categories with significant survival differences." (PMID 40608798, 2025). "Furthermore, based on the OncoVar online database, TRIM16, TRIM59, TRIM62, and TRIM71 genes were shown to act as tumor mutation drivers." (PMID 35873464, 2022). "A rational explanation for these observations is that TRIM16 plays a tumor suppressive role in GC and hindering its expression could result in higher expression levels for these three tumorigenic genes (β-catenin, CyclinD and BCL2)." (PMID 34452557, 2021).
tumor (continued). "Nevertheless, past experimental studies have supported TRIM16 as a de facto tumor suppressor that could inhibit cell migration and invasion in HCC." (PMID 31781161, 2019). "Recent studies have demonstrated that TRIM16 acts as a tumor suppressor in NB." (PMID 31820796, 2019). "Encouragingly, tumor immunohistochemical staining for TRIM16 expression showed a significant increase in the combination treatment group supporting our in vitro results which showed that induction of TRIM16 expression was required for the cytopathic effect of the combination." (PMID 27447557, 2016). "Since TRIM16 acts as a tumour suppressor, affecting cell proliferation and cell migration in different tissue types 16, 17, repressed expression of TRIM16 in SCC may contribute to the unrestrained proliferation of keratinocytes." (PMID 22009481, 2012). "In addition, evaluation of EMT markers in SCC tumours comparing wild-type, heterozygous and homozygous TRIM16 mice may provide insight into the molecular pathology of tumour development in vivo." (PMID 31342168, 2019). "Immunohistochemical analysis of tumor samples showed a significant increase in TRIM16 protein expression in the combination treated group after 21 days of treatment with representative immunohistochemistry for red chromogen TRIM16 staining is shown for each group." (PMID 27447557, 2016). "Previous studies have elucidated that TRIM21, TRIM26, TRIM35, TRIM50, and TRIM56 acted as tumor suppressors by inhibiting tumor cell proliferation, and TRIM3, TRIM16, TRIM21, TRIM25, and TRIM26 negatively regulated migration and invasion in HCC cells." (PMID 35142083, 2022). "TRIM3, TRIM16 and TRIM26 down-regulation contributes to poor prognosis in patients with HCC, suggesting the tumor suppressor function in HCC." (PMID 29898761, 2018). "In this study, we showed that TRIM16 expression was reduced in excised human actinic keratoses and further diminished in excised human SCC tumour tissue compared with normal skin." (PMID 22009481, 2012). "High nuclear staining of TRIM16 has been observed in differentiating ganglia cells which is absent in the tumour initiating cells." (PMID 31342168, 2019).
infection (5 papers, 2023 to 2025). The state of being infected such as from the introduction of a foreign agent such as serum, vaccine, antigenic substance or organism. "However, the role of TRIM16 in oxidative stress induced by infection of the highly pathogenic H5N1 avian influenza virus (HPAIV) is unclear." (PMID 36851605, 2023). "Summarizing, several genes were up-regulated in the cell lines that we considered to be a model of the primary site of infection: TRIM16, 47 in A549 and PC-3 after P. aeruginosa and Chlamydia spp." (PMID 37686095, 2023). "The results show that after infection with the H5N1 subtype influenza virus TRIM16 protein show significant down-regulation." (PMID 36851605, 2023). "For RSV, cells were infected at high and low MOIs of 0.1 and 0.01, respectively, and the enhancement in virus titres following TRIM16 KD was more pronounced following infection at the lower MOI." (PMID 37375542, 2023). "Importantly, a higher MOI was generally required for infection of cells with constitutive overexpression of CTRL or TRIM16, perhaps as a result of their different culture conditions (i.e., in the presence of hygromycin) when compared to cells with DOX-inducible overexpression." (PMID 37375542, 2023). "In control PHH cells treated with dimethyl sulfoxide (DMSO), p62, and TRIM16 were primarily localized in the cytoplasm regardless of the infection status of the cells." (PMID 38780261, 2024). "Each of the different DOX-inducible TRIM16 and CTRL cell lines was then cultured overnight in the presence (DOX) or absence (No DOX) of DOX before infection with RSV, IAV, or HSV-1 and viral titres determined in cell-free supernatants at 24 (IAV) or 48 (RSV, HSV-1) hpi." (PMID 37375542, 2023). "However, in cells constitutively overexpressing TRIM16, no virus growth was observed in cells infected with RSV, PIV-3, or IAV, and only limited virus growth was observed following infection with HMPV or HSV-1." (PMID 37375542, 2023).
TRIM16 also shares sentences with these, for which no sentence is quoted: non-small cell lung carcinoma (3 papers); heart failure (2); hepatocellular carcinoma (2); Arthritis (1); breast tumors (1); cardiomyopathy (1); cervical carcinoma (1); depression (1); gouty arthritis (1); hypertrophy (1); injury (1); ischemic stroke (1); myocardial ischemia (1); non‐alcoholic fatty liver disease (1); Obesity (1); periodontal disease (1); prostate tumors (1); skin papilloma (1); spastic ataxia (1).